UPK1A (uroplakin 1A)
Diseases named in the same sentence as UPK1A in open-access papers:
UPK1A is named in the same sentence as 34 diseases in open-access papers, as found by Europe PMC text mining. Sharing a sentence is not in itself a finding about the gene and the disease. The quoted sentences say what the papers report.
gastric cancer (5 papers, 2014 to 2021). A primary or metastatic malignant neoplasm involving the stomach. "Subsequently, using immunohistochemistry analysis for paraffin specimens, with large series of gastric cancer patients (n = 445), we observed that the low UPK1A expression was associated with histological grade (P = 0.022), lymph node metastases (P<0.001) and UICC stage (P = 0.008)." (PMID 24698999, 2014). "UPK1A was down-regulated and identified as a tumor suppressor in esophageal squamous cell carcinoma 6, colorectal cancer 25, and gastric cancer." (PMID 33046996, 2020). "The function of UPK1A in cell cycle, migration, and invasion was investigated by overexpressing UPK1A in the MKN45 gastric cancer cell line." (PMID 24698999, 2014). "Thus, UPK1A could be a potential favorable biomarker associated with gastric cancer prognosis." (PMID 24698999, 2014). "Univariate analysis revealed that UPK1A expression was a significant prognostic factor for gastric cancer patients (p = 0.045)." (PMID 24698999, 2014). "The mechanism of UPK1A in gastric carcinoma remains to be fully explored, and therefore our future studies will focus on this mechanism and the relationship between UPK1A and MMP7 in GCs." (PMID 24698999, 2014). "Tspan20, also known as uroplakin 1B (UPK1B), promotes the invasion and metastasis of bladder cancer via regulation of the Wnt/β-catenin pathway, while the reduced expression of Tspan21 (UPK1A) might play a role in the progression of gastric cancer." (PMID 35046772, 2021). "UPK1A was also found to be down-regulated in colorectal cancer and gastric cancer." (PMID 33046996, 2020). "In gastric cancer, UPK1A was reported to be downregulated, and increased expression of UPK1A could inhibit cell migration and invasion." (PMID 32368305, 2020). "Further study is needed to fully evaluate whether UPK1A could serve as a potential target for gene therapy in the treatment of gastric cancer." (PMID 24698999, 2014). "The findings may suggest that decreased UPK1A expression might help identify gastric cancer patients with poor prognosis and more lymph node metastases." (PMID 24698999, 2014). "Furthermore, we investigated the relationship of UPK1A expression and the disease-specific patient survival of the 445 patients with gastric cancer." (PMID 24698999, 2014). "The reduced expression of UPK1A might play a role in the progression of gastric cancer." (PMID 24698999, 2014). "Therefore, UPK1A may serve as a potential tumor-suppressor gene in gastric cancer." (PMID 24698999, 2014). "However, the prognostic and clinicopathological significance of UPK1A in human gastric carcinoma (GC) has not yet been investigated." (PMID 24698999, 2014).
bladder cancer (4 papers, 2020 to 2024). "The marked decrease of both prevalence and intensity of Upk1a and Upk1b immunostaining from non-invasive (pTa) to muscle-invasive carcinomas (pT2-4) reflects a striking loss of Upk expression during bladder cancer progression." (PMID 37777995, 2024). "Analysis of urine samples from patients with urothelial BCa revealed a significant correlation of the RNA-ratio OP18:uroplakin 1A with bladder cancer." (PMID 32614890, 2020). "This test revealed matching RNA levels of OP18 and UPK1A, respectively, and suggested the validity of this cell-based system to study the role of OP18 for malignant cell proliferation of bladder cancer." (PMID 32614890, 2020).
esophageal squamous cell carcinoma (4 papers, 2014 to 2022). Esophageal squamous cell carcinoma (ESCC) is a type of esophageal carcinoma (EC) that can affect any part of the esophagus, but is usually located in the upper or middle third. "In esophageal squamous cell carcinoma, UPK1A was found to be downregulated, and UPK1A could inhibit cell proliferation, clonogenicity, cell motility and tumor formation." (PMID 32368305, 2020).
breast carcinoma (3 papers, 2020 to 2024). "It is also of note that Upk1a/Upk1b staining is only very rarely seen in breast cancer (0%–4%) and in salivary gland tumors (0%–10%)." (PMID 37777995, 2024). "Here, we found that miR-658 was upregulated in breast cancer cell lines, and circNFIC could directly interact with miR-658 and act as a sponge for miR-658 to regulate the expression of UPK1A, a target gene of miR-658." (PMID 32368305, 2020). "Here, we found that UPK1A was downregulated in breast cancer cell lines and that circNFIC could sponge miR-658 to regulate the expression of UPK1A and the progression of breast cancer." (PMID 32368305, 2020). "circNFIC could be used as a promising prognostic biomarker for breast cancer patients, and therapeutic targeting of the circNFIC/miR-658/UPK1A network may be a potential strategy for the treatment of breast cancer." (PMID 32368305, 2020). "Thus, we explored UPK1A expression in breast cancer cell lines and found that UPK1A was downregulated." (PMID 32368305, 2020).
urothelial carcinoma (3 papers, 2013 to 2024). A malignant neoplasm derived from the transitional epithelium of the urinary tract (urinary bladder, ureter, urethra, or renal pelvis). "Uroplakin-1a (Upk1a) and uroplakin-1b (Upk1b) have recently been identified as diagnostic markers for the distinction of urothelial carcinomas from other solid tumor entities." (PMID 37777995, 2024). "Both Upk1a and Upk1b were recently identified as useful IHC markers for the distinction of urothelial carcinomas from its morphological differential diagnoses in studies investigating 6929 and 14,061 tumors from more than 110 different cancer entities." (PMID 37777995, 2024). "We thus studied the relationship between Upk1a and Upk1b immunostaining and clinicopathological parameters of disease progression as well as patient outcome in more than 2700 urothelial carcinomas in a tissue microarray (TMA) format." (PMID 37777995, 2024). "In recent studies on more than 6500 tumors from more than 100 different cancer types, Upk1a and Upk1b have been identified as potential markers for the distinction of urothelial carcinomas from other tumor entities." (PMID 37777995, 2024). "The results of our study confirm a diagnostic utility of Upk1a and Upk1b IHC for the distinction of urothelial carcinomas from other tumor entities and also suggest a prognostic utility of Upk1a/Upk1b measurement as a part of a panel that distinguishes a “luminal” urothelial cancer phenotype." (PMID 37777995, 2024). "In summary, the results of our study demonstrate that Upk1a and/or Upk1b immunohistochemistry can complement GATA3 for the distinction of urothelial carcinomas." (PMID 37777995, 2024). "In summary, the results of our study demonstrate that Upk1a and/or Upk1b IHC can well complement GATA3 for the distinction of urothelial carcinomas." (PMID 37777995, 2024). "Upk1a/Upk1b staining was observed in 32% of GATA3 negative pT2-4 cancers and GATA3 staining was seen in 43% of Upk1a/Upk1b negative pT2-4 urothelial carcinomas." (PMID 37777995, 2024).
colorectal cancer (2 papers, 2020). A primary or metastatic malignant neoplasm that affects the colon or rectum. "In colorectal cancer, UPK1A was also downregulated, and low expression of UPK1A was significantly associated with poorer survival." (PMID 32368305, 2020).
lung carcinoma (2 papers, 2020 to 2023). "Through genomic analysis we found that genomic mutations especially amplification of UPK1A gene was usually observed in various cancers, including uterine carcinosarcoma, ovarian serous cystadenocarcinoma, lung cancer, pancreatic adenocarcinoma." (PMID 33046996, 2020). "However, genomic mutations especially amplification of UPK1A gene was usually observed in various cancers, including uterine carcinosarcoma, Ovarian serous cystadenocarcinoma, lung cancer, pancreatic adenocarcinoma and HCC." (PMID 33046996, 2020). "But TSPAN11, UPK1B, and UPK1A are currently not related to lung cancer research." (PMID 37516981, 2023).
urinary bladder transitional cell carcinoma (2 papers, 2020 to 2024). "The mechanisms underlying the up-regulation of UPK1A in cancer like urinary bladder transitional cell carcinoma is largely unknown." (PMID 33046996, 2020).
carcinoma-in-situ (1 paper, 2019). "After ex vivo imaging, the progression of bladder carcinogenesis from normal urothelium to hyperplasia, carcinoma-in-situ and carcinoma with increased Ki67 and decreased uroplakin-1A expression was confirmed by histology and immunohistochemistry analysis." (PMID 31775672, 2019).
COVID-19 (1 paper, 2024). A disease caused by infection with severe acute respiratory syndrome coronavirus 2. "Therefore, the objective of our study is to investigate genetic variants in the genes AQP3, ARHGAP27, ELF5, IFNAR2, LIMD1, OAS1 and UPK1A, which were selected due to the association of these genes with the severity of COVID-19, in a sample of Amazonian indigenous peoples." (PMID 38543725, 2024). "Seven new genes (AQP3, ARHGAP27, ELF5, IFNAR2, LIMD1, OAS1 and UPK1A) were related to the severity of COVID-19 in populations of European origin." (PMID 38543725, 2024). "Another study developed in 34 Spanish hospitals with 11,939 positive cases of COVID-19 identified the relationship of the AQP3, ARHGAP27, ELF5, IFNAR2, LIMD1, OAS1 and UPK1A genes with the severity of the disease." (PMID 38543725, 2024).
gastric adenocarcinoma (1 paper, 2014). "Real-time quantitative PCR (RT-qPCR), western blotting, and immunohistochemical (IHC) staining methods were used to analyze the expression of UPK1A in primary gastric adenocarcinoma tissue samples." (PMID 24698999, 2014). "The aim of this study was to investigate the expression and prognostic significance of Uroplakin1A (UPK1A) in gastric adenocarcinoma patients." (PMID 24698999, 2014).
hepatocellular carcinoma (1 paper, 2020). A malignant tumor that arises from hepatocytes. "However, the functions of UPK1A and its underlying mechanisms in hepatocellular carcinoma (HCC) remain poorly understand." (PMID 33046996, 2020).
liver cancer (1 paper, 2020). An epithelial or non-epithelial malignant neoplasm that arises from the liver. "The results showed that a high expression level of UPK1A was association with gene signatures of poor liver cancer survival, which suggested that high expression of UPK1A correlated with poor prognosis in patients with HCC." (PMID 33046996, 2020).
lung adenocarcinoma (1 paper, 2020). A carcinoma that arises from the lung and is characterized by the presence of malignant glandular epithelial cells. "Consistently, cancers with high UPK1A gene amplification frequency exhibited high expression of UPK1A, including Lung squamous cell carcinoma, Lung adenocarcinoma, Uterine Corpus Endometrial Carcinoma, pancreatic adenocarcinoma and HCC." (PMID 33046996, 2020).
lymph node metastasis (1 paper, 2014). "The down-regulation of UPK1A was significantly associated with lymph node metastasis in GC (P<0.01)." (PMID 24698999, 2014).
metastasis (1 paper, 2014). The spread or migration of cancer cells from one part of the body (where they first appeared) to another. "Our findings indicate that UPK1A may play a role in tumor suppression, and is closely correlated with survival and lymph node metastasis in GC patients." (PMID 24698999, 2014).
urinary tract infection (1 paper, 2022). "Uroplakin 1a (TSPAN21) and Uroplakin 1b (TSPAN20) have been found to attach to the type 1 fimbriae, FimH adhesin of uropathogenic Escherichia coli that invaded the bladder epithelial cells leading to urinary tract infections in humans." (PMID 36101528, 2022).
tumor (15 papers, 2012 to 2025). "We next performed GSEA analysis on tumor samples from TCGA dataset to explore the mechanisms underlying UPK1A involved in HCC glycolysis and proliferation." (PMID 33046996, 2020). "Parameters for luminal tumor phenotype—which was linked to favorable disease outcome in studies analyzing RNA—such as uroplakin 1a, uroplakin 1b, or GATA3 were also unrelated to patient outcome in our cohort of more than 600 muscle-invasive carcinomas in recent studies." (PMID 39680294, 2025). "Results showed that some of the proteins found in EVs were shared among these cancer types, while others were tumour‐specific, and with respect to UC, the EVs expressed high levels of UPK1A, UPK1B, UPK2 and UPK3B." (PMID 35838333, 2022). "In the present study, we found that UPK1A was highly expressed in HCC tumor tissues compared with adjacent non-tumor tissues." (PMID 33046996, 2020). "The results revealed that the protein levels of UPK1A were significantly reduced in tumor tissue samples, compared with levels in normal paracancerous tissues (P<0.01)." (PMID 24698999, 2014). "The positive UPK1A expression was localized to the cytoplasm, and reduced cytoplasmic UPK1A was observed in the tumor tissues, especially in the poorly differentially tumor tissues." (PMID 24698999, 2014). "The results showed that the immuno-staining of UPK1A is varied in tumor tissues and adjacent non-tumor regions." (PMID 24698999, 2014). "Compared with matched adjacent non-tumor, the expression of UPK1A in fresh surgical specimens was reduced, which was confirmed by RT-qPCR (P<0.01) and western blotting analysis (P<0.01)." (PMID 24698999, 2014). "Uroplakin 1A (UPK1A) codes a cell-surface protein that may play a role in normal bladder epithelial physiology and possible tumor suppression." (PMID 38584916, 2024). "UPK1A has long been reported to be a tumor suppressor gene in multiple cancers and could be a useful marker for diagnosis and prognostic prediction." (PMID 32368305, 2020). "UPK1A was highly expressed in HCC tissues compared with adjacent non-tumor tissues." (PMID 33046996, 2020). "UPK1A was barely expressed in adjacent non-tumor liver sample." (PMID 33046996, 2020). "To explore the expression of UPK1A in HCC, we examined UPK1A expression in 17 paired fresh HCC tissues and adjacent non-tumor tissues (17-Patient cohort) using qRT-PCR." (PMID 33046996, 2020). "A similar result was found when UPK1A expression was re-assessed in 50 paired HCC tissues and adjacent non-tumor samples (P = 0.014)." (PMID 33046996, 2020). "While UPK1A-specific RNA sequences were less abundant in urine samples from G3 BCa patients when compared to G2 BCa patients, the high level of urinary OP18-specific RNA sequences increased with tumor invasiveness, thereby representing the determining factor for an increased OP18:UPK1A mRNA-ratio." (PMID 32614890, 2020). "There was a significant difference in the average expression level of UPK1A mRNA between the tumor tissues and the paired non-tumors (P<0.01), and the expression of UPK1A was lower in tumor tissues." (PMID 24698999, 2014). "Quantitative RT-qPCR was performed on 51 pairs of surgical specimens (tumor and adjacent non-tumor tissue samples) to examine the mRNA expression of UPK1A." (PMID 24698999, 2014). "Furthermore, UPK1A inhibits the nuclear translocation of β-catenin and can serve as an antagonist to matrix metalloproteinase 7 (MMP7), thereby playing a prominent role in tumor suppression." (PMID 24698999, 2014). "Among them, RAB11A expression was correlated with the expression of UPK1A and UPK2, two urothelium marker genes also down-regulated in this tumor group (data not shown)." (PMID 22724020, 2012). "Transcriptional profiling classified the Ta tumours as luminal (high expression of luminal markers such as GATA3, PPARG, FOXA1 and XBP1 as well as differentiation markers such as UPK1A and KRT20) as well as non-aggressive (high expression of SKAP2, FABP4, MBNL2 and ID1)." (PMID 28916750, 2017).
cancer (5 papers, 2015 to 2024). A tumor composed of atypical neoplastic, often pleomorphic cells that invade other tissues. "A subset analysis revealed a tendency towards a favorable prognosis in pT4 carcinomas with high Upk1a levels (p = 0.0999) while such an association was not seen in pT2 and pT3 cancers." (PMID 37777995, 2024). "Within pT2-4 carcinomas, high expression of Upk1a and Upk1b was linked to nodal metastasis and lymphatic vessel infiltration (p < 0.05) but unrelated to patient outcome." (PMID 37777995, 2024). "In addition, a comparison with GATA3 expression was conducted to further evaluate the diagnostic potential of Upk1a and Upk1b for identifying cancers of urothelial origin." (PMID 37777995, 2024). "GATA3 and Upk1a/Upk1b immunostaining showed a strong statistical correlation in our 1596 pT2-4 carcinomas with data on all three markers (p < 0.0001)." (PMID 37777995, 2024). "There seemed to be more complex roles for UPK1A regarding development and progression in different cancer types." (PMID 33046996, 2020). "Absence of GATA3/Upk1a/b staining was significantly linked to poor patient survival in the subgroup of 126 pT4 carcinomas (p = 0.0004) but not in pT2 and pT3 cancers." (PMID 37777995, 2024). "The fraction of Upk1a/Upk1b positive cases decreased slightly from pTaG2 low-grade (88% positive for Upk1a/87% positive for Upk1b) and pTaG2 high-grade (92%/89%) to pTaG3 (83%/88%; p > 0.05) and was lower in muscle-invasive (pT2-4) carcinomas (42%/64%; p < 0.0001/p < 0.0001 for pTa vs. pT2-4)." (PMID 37777995, 2024). "Furthermore, a progressive loss of Upk1a/b expression during stage progression and a prognostic role of the combination GATA3/Upk1a/Upk1b in pT4 carcinomas is evident." (PMID 37777995, 2024). "It has been reported that UPK1A was dysregulated in various cancer." (PMID 33046996, 2020). "However, the potential role of UPK1A in cancer development and progression remains quite contradictory." (PMID 33046996, 2020). "Uroplakin 1A (UPK1A) has recently been found dysregulation in many cancers." (PMID 33046996, 2020). "That the combination of Upk1a/Upk1b and GATA3 resulted in an even stronger association with patient survival and that this link was still completely limited to pT4 cancers may suggest that IHC panels identifying luminal type pT4 carcinomas may have clinical utility in the future." (PMID 37777995, 2024). "Taken together, dysregulations of UPK1A may play crucial roles in cancers." (PMID 33046996, 2020). "There were significant associations between Upk1a, Upk1b and GATA3 immunostaining (p < 0.0001 each), but 11% of GATA3 negative cancers were Upk1a/b positive and 8% of Upk1a/b negative cancers were GATA3 positive." (PMID 37777995, 2024). "Within pT2-4 carcinomas, only 11.2% of 706 Upk1a positive cancers were Upk1b negative while 41.2% of 1,076 Upk1b positive cancers were Upk1a negative (p < 0.0001)." (PMID 37777995, 2024). "The combined analysis of Upk1a and Upk1b revealed a link between high Upk1a/Upk1b expression and favorable patient prognosis in pT4 (p = 0.0365) but not in pT2 and pT3 carcinomas." (PMID 37777995, 2024). "However, GATA3 positivity was found in 31.5% of 476 Upk1a/Upk1b negative while Upk1a/Upk1b positivity was observed in 42.7% of 569 GATA3 negative pT2-4 cancers." (PMID 37777995, 2024).
UPK1A also shares sentences with these, for which no sentence is quoted: cystitis (3 papers); infection (2); cervical carcinoma (1); glaucoma (1); gonococcal infection (1); invasive carcinoma (1); lung squamous cell carcinoma (1); nasopharyngeal carcinoma (1); ovarian serous cystadenocarcinoma (1); pancreatic adenocarcinoma (1); pyelonephritis (1); retinal degeneration (1); salivary gland tumors (1); uterine carcinosarcoma (1); uterine corpus endometrial carcinoma (1).